MALAT1 (metastasis associated lung adenocarcinoma transcript 1)
Diseases named in the same sentence as MALAT1 in open-access papers (continued):
Sharing a sentence is not in itself a finding about the gene and the disease.
Hyperglycemia (continued). "Malat1 is highly conserved, and previous studies found that Malat1 is closely related to diseases, such as hyperglycemia, leukemia, and acute mononucleosis." (PMID 35309141, 2022). "An example can be found in MALAT-1, which is one of the most studied lncRNAs expressed in ECs, where it regulates hyperglycaemia-induced inflammatory process." (PMID 33651185, 2021). "This is in agreement with Puthanveetil and co-workers’ report that MALAT1 is involved in hyperglycemia by inducing inflammatory cytokines such as tumor necrosis factor-alpha (TNF-α)." (PMID 33670447, 2021). "Another study indicated that MALAT1 regulated hyperglycemia induced inflammatory process in endothelial cells." (PMID 34796177, 2021). "Among these, MALAT1, a conserved lncRNA, was significantly upregulated in an RF/6A cell model of hyperglycemia, in the aqueous humors, and in the fibrovascular membranes of diabetic patients." (PMID 30909482, 2019). "As discussed more fully below, we observed elevated MALAT1 expression in activated LX-2 cells, concordant with these findings, and demonstrated that MALAT1 expression is modulated by hyperglycemia in HepG2 cells." (PMID 30134610, 2018). "A recent study indicated that MALAT1 regulated hyperglycaemia induced inflammatory process in endothelial cells." (PMID 28643459, 2017). "In this study we have shown that lncRNA MALAT1 is induced following short-term hyperglycaemia which turns on early inflammatory events in the endothelium through SAA3." (PMID 25787249, 2015). "It is possible that, either MALAT1 has a shorter half-life or their stability is influenced by hyperglycaemia at a longer time period." (PMID 25787249, 2015). "Overall, our findings indicate that MALAT1 is able to rescue the retina from hyperglycemia-induced degeneration and significantly improve retinal visual function." (PMID 25356875, 2014). "The ARPE-19 cell line was used to confirm that hyperglycemia induced the expression of MALAT1 in vitro, and the corresponding expression of TNF-α, MCP-1, ICAM-1, and VEGF was also significantly increased, while the expression of these factors was significantly inhibited after silencing MALAT1." (PMID 40128064, 2025). "However, changes in MALAT1 expression have also been observed in other types of diseases, such as hyperglycemia, diabetic retinopathy, proliferative vitreoretinopathy, liver fibrosis, and hypertension." (PMID 38674413, 2024). "MALAT1 silencing or miR-205 overexpression appears to attenuate hyperglycemia-induced EMT." (PMID 36827547, 2023). "Their study demonstrated that miR-203a-3p overexpression decreased angiogenesis and reduced HIF-1α and VEGFA levels in hyperglycemia-stimulated HRMECs and showed that the decreased miR-203a-3p level could be reversed by MALAT1 silencing." (PMID 37762249, 2023). "In summary, lncRNA MALAT1 is involved in the hyperglycemia-induced EMT of human HaCaT cells." (PMID 36827547, 2023). "Furthermore, a recent study presents that si-MALAT1 alleviates collagen accumulation and inflammation in hyperglycemia cardiac fibroblasts and DCM mice via the Hippo–YAP pathway and CREB." (PMID 33889601, 2021). "In addition, MALAT1 has been reported to promote inflammation in septic heart damage, systemic lupus erythematosus, and hyperglycemia-induced inflammatory process." (PMID 33134293, 2020). "To address whether differential methylation patterns exist in the MALAT1 promoter in hyperglycemia, we cultured HRECs in NG and HG conditions and performed a genome-wide methylation analysis." (PMID 29695738, 2018). "MALAT1 expression was also increased in activated LX-2 cells and upregulated by hyperglycemia." (PMID 30134610, 2018). "To examine whether hyperglycaemia induced inflammatory markers induction by MALAT1 requires SAA, we tried silencing MALAT1 and added Apo–SAA, a recombinant protein." (PMID 25787249, 2015).
Hyperglycemia (continued). "Hyperglycemia could significantly increase retinal vascular leakage, whereas intraocular injection of MALAT1 shRNA could alleviate vascular leakage in diabetic rats." (PMID 25356875, 2014). "However, the effect of exosomal MALAT1 derived from macrophages induced by hyperglycemia on vascular calcification (VC) remains unclear." (PMID 41440015, 2025). "Furthermore, hyperglycemia and elevated FFA levels stimulate pancreatic and duodenal homeobox 1 (PDX1) expression, which in turn enhances the transcription of metastasis-associated lung adenocarcinoma transcript 1 (MALAT1)." (PMID 40392981, 2025). "However, whether MALAT1 is required for EMT under hyperglycemia in keratinocytes has yet to be elucidated." (PMID 36827547, 2023). "Another proinflammatory mechanism due to hyperglycemia mediated by MALAT1 is the upregulation of serum amyloid antigen 3 (SAA3), which stimulates the production of proinflammatory cytokines TNF-α and IL-6, promoting endothelial inflammation, which may lead to CVD." (PMID 34298896, 2021). "This study identifies a previously unrecognized exosomal lncRNA-mediated pathway involving MALAT1, miR-143-3p, and MGP that regulates the response of vascular smooth muscle cells (VSMCs) to hyperglycemia." (PMID 41440015, 2025). "MALAT1 also regulates ZEB2 by binding miR-145 and promoting EMT in hyperglycemia stimulated HK-2 cells." (PMID 36827547, 2023). "MALAT1 regulates the expression of the cytokines interleukin 6 (IL-6) and tumor necrosis factor-alfa (TNF-α) by activating serum amplitude antigen 3 (SAA3) in arterial hyperglycemia." (PMID 38674413, 2024). "We hypothesize that the lncRNA MALAT1 binds to miR-205 to elevate the expression of the target gene ZEB1, thereby inducing EMT under hyperglycemia conditions." (PMID 36827547, 2023). "A study revealed that MALAT1 and GRP78 expression in vascular endothelial cells (RVECs) may be elevated by hyperglycemia, and it showed that GRP78 overexpression led to angiogenesis, ERS and inflammation in RVECs." (PMID 37762249, 2023). "miR-23c, as a target of lncRNA MALAT1, could directly repress its target ELAVL1 and inhibit hyperglycemia-induced cell pyroptosis." (PMID 31481972, 2019). "The novelty of our study is that the combined use of two lncRNAs, LIPCAR and MALAT1, measured in the plasma of ACS patients, may discriminate vulnerable CAD from SA, correlate with hyperglycemia in UA patients, and predict unfavorable evolution (MACE) of STEMI patients." (PMID 37569451, 2023). "However, the effect of hyperglycemia on the regulation of macrophage-derived exosomal MALAT1 and its possible regulatory mechanism in hyperglycemia have not been previously characterized." (PMID 35163020, 2022). "Moreover, hyperglycemia and elevated levels of FFAs also induce an increase in the transcriptional factor pancreatic and duodenal homeobox 1 (PDX1), which, in turn, increases the transcription of MALAT1 and can induce β-cell dysfunction through the PDX1/MALAT1/PTBP1 pathway." (PMID 34298896, 2021).
liver fibrosis (40 papers, 2016 to 2025). "MALAT1 (Metastasis Associated Lung Adenocarcinoma Transcript 1) is another broadly recognized lincRNA, which is highly expressed in hepatic fibrosis tissues and interacts with DNMT1 both in human and mice." (PMID 39036601, 2024). "Simultaneously, the role of EVs-Lnc-MALAT1 in liver fibrosis and the associated fibrogenic mechanism were investigated in the human hepatic stellate cells LX-2 in vitro and in human fibrotic liver tissues." (PMID 35237178, 2022). "In liver fibrosis, numerous lncRNAs such as MALAT1, LFAR1, H19, and NEAT1 was implicated in various inflammatory chemokine pathways including transforming growth factor β (TGF-β), activation of macrophage, and C-X-C motif chemokine ligand 5 (CXCL5)." (PMID 34938356, 2021). "Metastasis-associated lung adenocarcinoma transcript 1 (MALAT1), a lncRNA that is upregulated in hepatic fibrosis and activated HSC, was present in exosomes released by L-02 human fetal hepatocytes exposed to fibrosis-causing arsenite." (PMID 34202136, 2021). "In the context of fibrosis, the function of lncRNA metastasis-associated lung adenocarcinoma transcript 1 (MALAT1) has been well-studied in cardiac and in hepatic fibrosis." (PMID 34054586, 2021). "For instance, metastasis-associated lung adenocarcinoma transcript 1 (MALAT1) contributes to liver fibrosis via the regulation of RAS-related C3 botulinum substrate 1 (Rac1) and miR-101b." (PMID 27610008, 2016). "Therefore, our data suggest Malat1 is not only a potential therapeutic target for schistosoma-associated liver fibrosis but also a biomarker for assessing the response to PZQ chemotherapy." (PMID 39363237, 2024). "Another finding in our present study is that plasma EVs-Lnc-MALAT1 may be used as a diagnostic biomarker for liver fibrosis." (PMID 35237178, 2022). "In our current study, EVs-Lnc-MALAT1 in the plasma of liver fibrosis patients was detected to evaluate whether it had diagnostic values for liver fibrosis." (PMID 35237178, 2022). "Therefore, the diagnostic value of the plasma EVs-Lnc-MALAT1 in liver fibrosis was evaluated by ROC analysis." (PMID 35237178, 2022). "A role of MALAT1 in liver fibrosis via the regulation of the chemokine CXCL5 was also reported in a study investigating fibrosis in NASH patients." (PMID 40002783, 2025). "Increased MALAT1 expression in liver fibrosis and regulation of botulinum C3 substrate 1 (Rac1) expression by miR-101b have been demonstrated to affect the cell cycle and activation of primary hepatic stellate cells." (PMID 38674413, 2024). "MALAT1 expression was induced and positively associated with the pathological progression of MASLD and hepatic fibrosis." (PMID 39872125, 2024). "In a mouse model of CCl4-induced liver fibrosis, MALAT1 expression increased approximately 5.9-fold in HSCs and 2.7-fold in hepatocytes compared with that in controls." (PMID 39872125, 2024). "In arsenite-induced liver fibrosis, elevated Malat1 is involved in the activation of hepatic stellate cells via miRNA-26b." (PMID 39363237, 2024). "By exacerbating the progress of liver fibrosis, MALAT1 plays a crucial role in the pathogenesis of NAFLD." (PMID 36864020, 2023). "MALAT1 knockdown reversed free fatty acid -induced lipid accumulation in hepatocytes; moreover, MALAT1 promoted the progression of liver fibrosis." (PMID 38115130, 2023). "In our current study, the expression of Lnc-MALAT1 in the fibrotic liver tissues and in the plasma extracelllar vesicles (EVs) of liver fibrosis patients was detected by FISH and qRT-PCR." (PMID 35237178, 2022). "Lnc-MALAT1 was found to be enriched in the liver tissues of the liver fibrosis patients compared to in the liver tissues of the control patients, and mostly located within and surrounding the fibrotic lesions." (PMID 35237178, 2022).
liver fibrosis (continued). "ROC analysis of the plasma EVs-Lnc-MALAT1 levels in 60 cases of liver fibrosis patients and 46 control subjects in our current study revealed 65.6% of AUC, with 51.7% of sensitivity and 78.3% of specificity." (PMID 35237178, 2022). "Another study on nonalcoholic steatohepatitis fibrosis showed that MALAT1 plays a key role in liver fibrosis by regulating the chemokine CXCL5." (PMID 35769097, 2022). "Evidence shows that the long noncoding RNA metastasis-associated lung adenocarcinoma transcript 1 (Lnc-MALAT1) is associated with activation of hepatic stellate cells (HSCs) and liver fibrosis in animal and in vitro studies." (PMID 35237178, 2022). "Of these ceRNA mechanisms, LincRNA-p21 /MicroRNA-17-5p, lncRNA GAS5/miR-23a, LncRNA Gm5091/miR-27b/23b/24, and MALAT1/miR-101b have been suggested to contribute to the alleviation of liver fibrosis." (PMID 35902883, 2022). "For elucidation of the role of EVs-Lnc-MALAT1 in liver fibrosis, LX-2 cells were incubated with the EVs isolated from the plasma of patients in the high fibrosis group or from the control plasma, with TGF-β1 as a positive control." (PMID 35237178, 2022). "First, we detected the progressive up-regulations of METTL3 and MALAT1 in KCs from in vivo CCl4-induced liver fibrosis and from in vitro M1-polarized macrophages." (PMID 34839365, 2021). "When it comes liver fibrosis, several studies reveal multiple pro-fibrotic mechanisms of MALAT1 in HSCs." (PMID 34839365, 2021). "To assess the functional significance of MALAT1 in M1 macrophage activation and liver fibrosis, we injected either control shRNA (shNC) or MALAT1-specifid shRNA (shMALAT1) directly into mice before inducing liver fibrosis with CCl4." (PMID 34839365, 2021). "In this study, we reported not only the relevance of METTL3 (a protein, when dimerized with METTL14, responsible for m6A methylation of RNA molecules) to the pathogenesis of liver fibrosis, but its essential role in controlling the stability of lncRNA MALAT1." (PMID 34839365, 2021). "In short, MALAT1 promotes HSC activation by blocking SIRT1-mediated inhibition of the TGF-β signaling pathway in hepatic fibrosis." (PMID 35145971, 2021). "In conclusion, these findings highlight the role of MALAT1 in liver fibrosis and suggest a mechanism for fibrosis development." (PMID 34899344, 2021). "These phenomena suggest a role for MALAT1 in mediating the expression as well as the function of SIRT1 in regulating liver fibrosis." (PMID 34899344, 2021). "Concomitantly, we observed the increase of both MALAT1 and METTL3 in these cells, suggesting that the up-regulations of MALAT1 and METTL3 in macrophages were closely associated with the development of liver fibrosis." (PMID 34839365, 2021). "In conclusion, here we showed that the METTL3/MALAT1/PTBP1/USP8/TAK1 axis was activated in macrophages during the development of liver fibrosis." (PMID 34839365, 2021). "Like GAS5, lncRNA, including lncRNA-p21, PVT1, HOTAIR, and MALAT1, acts as a ceRNA regarding liver fibrosis." (PMID 32413995, 2020). "MALAT1 also acts as a ceRNA to sponge miR-101b, which mediates Rac1 expression contributing to liver fibrosis." (PMID 32413995, 2020). "In summary, MALAT1 can promote the HSC activation through blocking the SIRT1 mediated inhibition of TGF-β signaling pathway in the progression of hepatic fibrosis." (PMID 30534359, 2018). "The function of MALAT-1 has been studied in liver fibrosis where down-regulation of MALAT-1 in HSC decreased the expression of myofibroblast markers and restored the level of SIRT1." (PMID 30158867, 2018). "Together, these findings provide preliminary evidence supporting a role for functionally relevant differences in MALAT1 expression in the development of liver fibrosis related to NAFLD." (PMID 30134610, 2018). "Elevated Malat1 expression in infected HSCs reduces fibrosis by downregulating miR-96 and upregulating Smad7, thus providing a novel therapeutic target for schistosomiasis hepatic fibrosis." (PMID 39363237, 2024).
liver fibrosis (continued). "For analysis of correlation of the plasma EVs-Lnc-MALAT1 with liver fibrogenesis, the 60 liver fibrosis patients were further divided into a high fibrosis group (21 patients, scoring = 3–4) and a low fibrosis group (39 patients, scoring = 1–2) according to the pathological Ishak scoring." (PMID 35237178, 2022). "Plasma EVs with highly expressed Lnc-MALAT1 derived from high liver fibrosis patients up-regulated the expression of the fibrotic markers and enhanced the Wnt/β-catenin signaling in human hepatic stellate cells LX-2, and the fibrogenic effects in LX-2 were inhibited by Lnc-MALAT1 knock-down." (PMID 35237178, 2022). "The lncRNA MALAT1 promotes liver fibrosis by targeting the miR-181a/TLR4/NF-κB axis." (PMID 35890132, 2022). "However, future efforts should be devoted to elucidating other regulatory mechanisms and clinical implications of MALAT1 in liver fibrosis." (PMID 34899344, 2021). "High MALAT1 expression may promote the progression of liver fibrosis in NASH patients via mechanisms relating to inflammatory chemokines." (PMID 32098245, 2020). "MALAT1 can promote the activation of HSCs by blocking the silent information regulator 1 (SIRT1)-induced inhibition of the TGF-β1 signaling pathway in the progression of liver fibrosis." (PMID 32326098, 2020). "Further, knockdown of Malat1 expression in CCl4-treated mice corresponded with a 54% decrease in collagen accumulation, suggesting that this lncRNA plays a role in the progression of liver fibrosis in mice." (PMID 30134610, 2018). "Moreover, schistosome infection significantly induced the expression of miRNA-96, which was opposite to that of Malat1, implying the Malat1-mediated inhibition of hepatic fibrosis might be through miRNA-96." (PMID 39363237, 2024). "Notably, pre-transfection of siRNA specific for Lnc-MALAT1 into the cells inhibited the fibrosis plasma EVs-induced expressions of these molecules (Lane 6), demonstrating that the enhanced effects by the plasma EVs from the liver fibrosis patients were Lnc-MALAT1-depentent." (PMID 35237178, 2022). "Sirius red staining of collagen in mouse liver tissue resulted in the observation that mice transduced by silencing MALAT1 showed a 54% downregulation of collagen accumulation compared to CCl4-treated mice, reflecting the role of MALAT1 in accelerating the progression of liver fibrosis in vivo." (PMID 34899344, 2021). "The results demonstrated that lncRNA-H19, -MALAT1, -PVT1, -P21 and -GAS5 all participated in liver fibrosis formation after schistosome infection." (PMID 39044218, 2024). "As expected, silencing lncRNA-H19, -MALAT1, and -PVT1, positively correlated with liver fibrosis, resulted in a significant decrease in α-SMA expression in JS-1 cells by approximately 46.59%, 41.02%, and 64.30% (P < 0.001), respectively." (PMID 39044218, 2024). "This study reveals the dynamic role of lncRNA-H19, -MALAT1, -PVT1, -P21, and -GAS5 in HSCs activation and liver fibrosis in S. japonicum-infected mice, regulated by the ICOSL/ICOS signaling pathway." (PMID 39044218, 2024). "The METTL3/MALAT1/PTBP1/USP8/TAK1 axis stimulated pyroptosis and inflammation of macrophages, leading to the aggravation of liver fibrosis." (PMID 37227534, 2023). "In mice with liver fibrosis induced by BDL, adenovirus with MALAT1 interfering RNA was injected through the tail vein to evaluate the effects of MALAT1 on HF." (PMID 37394585, 2023). "To understand the interaction between MALAT1 and METTL3 within macrophages during liver fibrosis, we first established an in vivo CCl4-induced liver fibrosis model." (PMID 34839365, 2021). "The signaling cascade METTL3/MALAT1/PTBP1/USP8/TAK1, by essentially stimulating pyroptosis and inflammation of macrophages, aggravates liver fibrosis." (PMID 34839365, 2021).